SNHG18 (small nucleolar RNA host gene 18)
Diseases named in the same sentence as SNHG18 in open-access papers (continued):
Sharing a sentence is not in itself a finding about the gene and the disease.
tumor (13 papers, 2019 to 2025). "SNHG18 functions as a negative regulator of tumor advancement, and its downregulation in HBV-related HCC removes the inhibition of key tumor suppressor pathways, leading to increased proliferation." (PMID 40625740, 2025). "Considering the limitations of in vitro experiments, we also used the nude mouse model of subcutaneous tumor transplantation to examine the role of SNHG18 in tumor growth in vivo." (PMID 36927398, 2023). "To this end, we collected 48 tumor and paired normal tissues, and quantitative real-time PCR (qPCR) was used to detect the relative expression of SNHG18." (PMID 36927398, 2023). "Our results contribute to understanding the regulatory behavior of lncRNAs in mCRPC and indicate SNHG18 and HELLPAR as master regulators and potential new diagnostic targets in this tumor." (PMID 37644825, 2023). "The lncRNA SNHG18 has been identified as a novel prognostic biomarker for tumours in previous studies, and high SNHG18 expression is correlated with a poor prognosis." (PMID 35359593, 2022). "Here, we provide evidence that downregulation of miR-211-5p is involved in the tumor-promoting activity of SNHG18 in NSCLC." (PMID 33500406, 2021). "The tumor-promoting activity of SNHG18 is largely attributed to antagonization of miR-211-5p and upregulation of BRD4." (PMID 33500406, 2021). "Moreover, we identified that overexpressing SNHG18 resulted in increased c-Myc-dependent p21 transcription, thereby inhibiting the tumorigenic growth of BC cells, which highlights the tumor suppressor function of SNHG18 in human BC." (PMID 36927398, 2023). "Further mechanistic studies revealed that SNHG18 may act as a tumor suppressor that exerts its antitumor effects by accelerating degradation of the transcription factor c-Myc, which allows for p21 accumulation, restraining BC development." (PMID 36927398, 2023). "In addition, SNHG18 expression showed an association with the clinical tumor grade and a negative correlation with mutation of isocitrate dehydrogenase 1 (IDH1)." (PMID 31798634, 2019). "The results showed that the expressions of MAFG-DT, SNHG18, and AL024508.1 were higher in tumor tissues, while the expressions of LINC00942, PSMB8-AS1, and AC116366.1 were higher in normal tissues." (PMID 35154117, 2022). "LINC00900, MIR210HG, MIR22HG, PVT1, and SNHG18 expression increased, whereas HAR1A, LINC00641, SLC25A21-AS1, and SNAI3-AS1 expression decreased with tumor grade." (PMID 34288803, 2021). "Although in this study, we show that SNHG18 is required for MKL1-dependent aggressive phenotype of NSCLC cells, other lncRNAs might also contribute to the tumor-promoting activity of MKL1." (PMID 33500406, 2021).
cancer (5 papers, 2019 to 2024). A tumor composed of atypical neoplastic, often pleomorphic cells that invade other tissues. "Long non-coding RNA (LncRNA) small nucleolar RNA host gene 18 (SNHG18) has been widely implicated in cancers." (PMID 38498586, 2024). "SNHG18 has been reported to be associated with growth, invasion, and drug resistance in a few cancers through multiple mechanisms." (PMID 36927398, 2023). "Few of the lncRNAs in the SNHG family are known to be negative regulators of the inflammatory response, while SNHG18, SNHG27, and SNHG28 are reported to be associated with different forms of cancer." (PMID 38426128, 2024). "Another research group investigated the role of small nucleolar RNA host gene 18 (SNHG18) in HCC and found it downregulated in cancer tissues compared with paired adjacent noncancerous tissues." (PMID 31416190, 2019).
SNHG18 also shares sentences with these, for which no sentence is quoted: prostate carcinoma (2 papers); atherosclerosis (1); co-infection (1); hepatitis B (1); Hypertension (1); lung carcinoma (1); peripheral arterial disease (1); Stroke (1).